ASPH (aspartate beta-hydroxylase)
Diseases named in the same sentence as ASPH in open-access papers (continued):
Sharing a sentence is not in itself a finding about the gene and the disease.
cancer (continued). "As a target of humoral immunity, ASPH on the surface of cancer cells can be bound by antibodies that mediate antibody-dependent cellular cytotoxicity (ADCC), complement dependent cytotoxicity (CDC), or antibody-dependent cellular phagocytosis (ADCP)." (PMID 32811566, 2020). "In bone-related cancer cell lines, ASPH has significant correlations with GSK3B (Pearson r = 0.50, p = 0.01) and CTNNB1 (Pearson r = 0.54, p = 0)." (PMID 33015050, 2020). "SMIs of ASPH have been developed and used to test the role of ASPH in a wide range of cancer models, including subcutaneous, orthotopic, and patient derived xenograft in vivo models." (PMID 32811566, 2020). "Of note, previous studies suggested that a relatively low level of ASPH expression in normal mature tissues, while abundant expression of ASPH in a variety of malignant tumors." (PMID 33015050, 2020). "The derivatives are potent inhibitors of the human 2‐oxoglutarate‐dependent oxygenase aspartate/asparagine‐β‐hydroxylase (AspH), which is a potential medicinal chemistry target for cancer therapy." (PMID 32330361, 2020). "A recent study showed a signature involving P4HA1, PLOD1, KDM3A, PLOD2, and ASPH predicted prognosis in various cancers including LUAD using bioinformatic analysis." (PMID 33299876, 2020). "There is an unmet need for further investigations into the biological functions of human AspH and its role in genetic diseases and cancer." (PMID 31659163, 2019). "Recently, a highly sensitive serum-based cancer diagnostics using ELISA has been developed, establishing ASPH (HAAH) as a potential biomarker for early-stage cancer." (PMID 31694640, 2019). "In this immunoassay, ASPH is detectable/significantly increased in cancer patients but undetectable or very tiny, if any, in health control donors." (PMID 31888763, 2019). "SNS-301 (formerly PAN-301) is a first-in-class immunotherapeutic cancer vaccine candidate targeting human aspartyl (asparaginyl) β-hydroxylase (ASPH)." (PMID 30400835, 2018). "As a result, ASPH represents a relevant target for CaEP-based cancer therapies.Additionally, prolonged stress from calcium overload and membrane disruption may contribute to the generation of reactive oxygen species (ROS)." (PMID 39980072, 2025). "Similarly to ALDH18A1, ASPH is also considered an oncogenic enzyme and is overexpressed in various cancers." (PMID 39858632, 2025). "This suggests that the therapeutic benefit of ASPH inhibition on cancer immunotherapy may be context-dependent and less effective when the immune system is already robustly activated." (PMID 40655119, 2025). "While some studies have used ASPH isoform 1-specific antibody for IHC, many have used the FB-50 antibody, and staining for ASPH with FB-50 has been shown to negatively correlate with survival in numerous studies of carcinomas; therefore, we used the FB-50 antibody in this study." (PMID 40149287, 2025). "Given the high expression of ASPH in HNSCC tumors, we evaluated if ASPH inhibitors affect cancer cell migration and invasion in line with previous studies showing that ASPH regulates cellular migration, invasion, epithelial–mesenchymal transition, apoptosis, and stemness in other cancers." (PMID 38732216, 2024). "By shedding light on previously unexplored cancer types, our study revealed the complex nature of ASPH-mediated Notch1 pathway regulation, but more importantly, highlighted the heterogeneous response of different cancer types to ASPH inhibition." (PMID 38817852, 2024). "ASPH is an oncogenic protein upregulated in many types of cancer." (PMID 38732216, 2024). "These pathways may be inhibited (GSK-3β 16) or activated (Notch1 10, SRC 15) by ASPH in a cell type-specific manner, leading to heterogeneous responses to ASPH inhibition in different cancer cell lines." (PMID 38817852, 2024).
cancer (continued). "The effects of ASPH inhibitors on Notch1 pathway activity, cyclin D1 expression, and nuclear morphology contribute to the understanding of the multifaceted effects of these inhibitors on cancer cell behavior." (PMID 38817852, 2024). "Cancer-associated fibroblasts (CAF) are an important mediator of cancer cell invasiveness and could contribute to the ASPH function in HNSCC." (PMID 38732216, 2024). "Notch1 signaling is a major pathway involved in cancer progression that is influenced by ASPH, but the underlying mechanisms of the influence of ASPH on the noncanonical pathway involved in this interaction have not been determined." (PMID 38817852, 2024). "Therefore, further studies regarding the level of ASPH expression in cancer tissues before and after NACT are required." (PMID 36982561, 2023). "ASPH was predominantly localized in the cytoplasm of cancer cells." (PMID 36982561, 2023). "In some types of invasive cancers, AspH is upregulated on the cell surface and might indirectly alter levels of EGFD hydroxylation, thus rendering AspH a proposed target for cancer treatment." (PMID 35700824, 2022). "similarly confirmed that ASPH could promote cancer cell re-interrogation migration, in vivo metastasis." (PMID 35965520, 2022). "ASPH is overexpressed in a wide variety of malignant tumors compared to normal human tissues." (PMID 36293298, 2022). "Fibulins might be relevant AspH downstream targets transmitting pathophysiologic-relevant effects of AspH upregulation in some cancer cells." (PMID 35700824, 2022). "ASPH is highly expressed during fetal development and is aberrantly upregulated in cancer cells." (PMID 35004304, 2021). "ASPH is a highly conserved β-dioxygenase enzyme that is overexpressed in several cancer types." (PMID 32295249, 2020). "AspH is reported to retain its catalytic activity on the cancer cell surface." (PMID 33069066, 2020). "However, according to our current data in vitro, it suggested that the treatment of ASPH inhibitor in patients with cancer need to be concerned because of their potential risks of bone loss or bone fracture." (PMID 33015050, 2020). "Based on the involvement of ASPH in Wnt signaling and cellular senescence in various cancers, we hypothesized that ASPH was involved in the bone formation and cellular senescence through regulating Gsk3β and β-catenin." (PMID 33015050, 2020). "AspH levels are up-regulated in certain cancers, e.g. hepatocellular carcinoma and glioma." (PMID 32107312, 2020). "The kcat/Km-value of AspH for 3-methyl-2OG is approximately three times higher than for 2OG, suggesting the feasibility of 2OG derivatives to selectively enhance AspH (or indeed other 2OG oxygenase) catalysis in cells or on the cell surface of cancer cells in the presence of 2OG." (PMID 34163896, 2020). "We thus aimed to screen APIs against AspH, with a special interest in cancer therapeutics." (PMID 33069066, 2020). "AspH is upregulated in hypoxia and is a prognostic marker on the surface of cancer cells." (PMID 34163896, 2020). "Moreover, in 1019 cancer cell lines, there were positive correlation between ASPH and RUNX2 or COL1A1." (PMID 33015050, 2020). "We report the effects of 316 small-molecule APIs, which are either components of approved human cancer therapeutics or of human cancer therapeutics under current or previous clinical investigation, on the catalytic activity of AspH, employing SPE-MS inhibition assays." (PMID 33069066, 2020). "One form of AspH is reported to be translocated to the tumor cell surface membrane, an observation correlating with enhanced cell motility and metastatic spread, and statistically reduced life expectancy of cancer patients (15, –, 18)." (PMID 32107312, 2020). "The focus was on APIs of cancer therapeutics as the identification of potential side-effects of these APIs through inhibiting AspH could render alternative explanations of their biological effects." (PMID 33069066, 2020).
cancer (continued). "Importantly, ASPH secreted by cancer cells and delivered by exosomes can be detected in biofluids (e.g., peripheral blood)." (PMID 31694640, 2019). "Therefore, ASPH is proposed to generate and maintain malignant phenotypes in cancer." (PMID 40149287, 2025). "Intrinsic characteristics of the cancer cell lines studied related to their histological origin, genetic instability leading to mutagenesis in various oncogenic pathways, and ASPH levels may be important sources of heterogeneous response to ASPH inhibition." (PMID 38817852, 2024). "According to our comprehensive bioinformatics results, we hypothesized that transcription factor CBX2 regulated ASPH may well be correlated with the carcinogenesis, cancer development, and unfavorable prognosis of KIRP through activation of Notch signaling pathway." (PMID 38702698, 2024). "Additionally, it was revealed that the overexpression of ASPH had been found in 70–90% of human solid tumors and that ASPH played a significant role in the malignant transformation of solid tumors via promoting proliferation, migration, and invasion of cancer cells." (PMID 38702698, 2024). "Therefore, we could draw the conclusion that ASPH might be regarded as a potential prognostic marker in cancer detection." (PMID 38702698, 2024). "Moreover, ASPH was found to be a potential target for cancer therapy and immunotherapy." (PMID 38702698, 2024). "Considering the proposed role of AspH upregulation in cancer progression, the identification of AspH substrates is important to inform on downstream signaling pathways, which may help to rationalize phenotypes associated with modulation of AspH levels or activity." (PMID 35700824, 2022). "It is unknown if this is a pattern seen across other cancers with ASPH expression." (PMID 35004304, 2021). "Thus, ASPH has been thought to be a potential therapeutic target for different cancers." (PMID 33015050, 2020). "Our study documents the upregulation of ASPH in HNSCC and shows that inhibition of ASPH activity by SMI MO-I-1151 limits HNSCC cancer cell migration and CAF-supported invasion into Matrigel." (PMID 38732216, 2024). "In this study, we therefore examine the expression of ASPH in HNSCC tumors, and we use a CAF-cancer cell co-culture spheroid model to evaluate the impact of ASPH inhibition on cancer cell invasion." (PMID 38732216, 2024). "ASPH, CDKN2A, E2F1, P3H1, and PTTG1 were identified as prognostic indicators of unfavorable outcomes within multiple cancer types." (PMID 37497116, 2023). "SCNV gain was identified in several genes such as E2F1, ASPH, BLVRA, and CEBPB across multiple cancers." (PMID 37497116, 2023). "We examined ASPH overexpressed in human GC tissues and cell lines, especially in NACT cancer tissues." (PMID 36982561, 2023). "Of note, positive correlations of ASPH with GSK3B and CTNNB1 have been found in the normal tissues, cancer tissues as well as cancer cell lines." (PMID 33015050, 2020). "ASPH stands out as an important therapeutic target in malignancy due to its high levels of expression on cancer cell surfaces and very low or absent expression in most normal cells." (PMID 40427168, 2025). "In order to further research the deep mechanism of ASPH regulating the development of cancer, we found that the Notch signaling pathway was the overlapped co-expression signal pathway." (PMID 38702698, 2024). "In summary, ASPH is overexpressed in a wide variety of malignant tumors, but it is not expressed in an appreciable amount in normal adult human tissue." (PMID 36293298, 2022). "AspH inhibition could to some extent account for the observed anti-cancer effects of venetoclax, even though this API inhibits its validated target enzyme, Bcl-2, significantly more efficient than AspH (~1000 fold selectivity)." (PMID 33069066, 2020). "Aspartate-β-hydroxylase (ASPH) is expressed at high levels in several malignant neoplasms of distinct histogenesis, and at very low levels or not at all in most normal cells and tissues." (PMID 31608231, 2019).
cancer (continued). "Despite its importance in healthy biology and cancer, few biochemical studies and no efficient substrates of isolated recombinant AspH have been reported to date." (PMID 31659163, 2019). "ASPH is an oncofetal antigen expressed prevalently in multiple human cancers but not in healthy adult tissue and that has not been targeted in any prior clinical studies." (PMID 30400835, 2018). "Through canonical and noncanonical pathways, ASPH inhibitors interrupt cell cycle progression by downregulating cyclin D1 and arresting cells in the G0/G1 cell cycle phase, thereby inhibiting the proliferation of cancer cells." (PMID 38817852, 2024). "In response to combination therapy, CXCL13 produced by ASPH+ expressing HCC or TNBC cell was capable of recruiting immune cells, especially CXCR5+/CD8+ TILs (including a proportion of CTLs), to participate in forming TLSs and to execute cytotoxicity against cancer cells." (PMID 35392977, 2022). "Notably, upon combination therapy, ASPH-MYC and downstream PD-L1/PD-1 signals were blocked; CTLs secreted CXCL13 could bind to CXCR5 on cancer cells and produce cytotoxicity against them efficiently." (PMID 35392977, 2022).
adenocarcinoma (2 papers, 2023 to 2025). A common cancer characterized by the presence of malignant glandular cells. "The expression of ASPH was positive in moderately differentiated adenocarcinoma and negative in well-differentiated adenocarcinoma." (PMID 40110547, 2025).
ASPH also shares sentences with these, for which no sentence is quoted: infection (3 papers); colon cancer (2); genetic diseases (2); Marfan syndrome (2); melanoma (2); non-small cell lung carcinoma (2); pancreatic neuroendocrine tumor (2); sarcoma (2); acute myeloid leukemia (1); amelanotic melanoma (1); Anxiety (1); aortic aneurysm (1); Arrhythmia (1); benign breast tumor (1); benign tumor (1); CADASIL (1); chronic kidney disease (1); Diabetes (1); ductal carcinoma in situ (1); Fibroadenoma (1); gallstones (1); intestinal polyp (1); intraductal papilloma (1); invasive ductal carcinoma (1); malignant glioma (1); MEGDEL syndrome (1); metastatic melanoma (1); Miller syndrome (1); mucinous cystadenocarcinoma (1); myopathies (1).
A further 13 diseases each share a sentence with ASPH in 1 paper.